SCD (stearoyl-CoA desaturase)
Diseases named in the same sentence as SCD in open-access papers (continued):
Sharing a sentence is not in itself a finding about the gene and the disease.
cancer (continued). "However, inhibition of FA desaturation following ablation of SCD causes ER stress, cell cycle inhibition and apoptosis in cancer cells." (PMID 24203995, 2013). "Indeed, SCD overexpression is implicated in metabolic diseases such as diabetes, obesity, insulin resistance, hypertension, and hypertriglyceridemia as well as in various human cancer cells." (PMID 34959675, 2021). "Finally, regarding SCD, which catalyzes the rate limiting step in the production of monounsaturated fatty acids (MUFAs), whose levels are directly associated with replication rates in cancer cells." (PMID 30913248, 2019). "Additionally, SCD inhibition causes cancer cell death by depleting monounsaturated fatty acids." (PMID 25243088, 2014). "SREBP protects cancer cells from lipotoxicity and ER stress induction by maintaining de novo lipid synthesis and desaturation via SCD." (PMID 40814339, 2025). "In cancer, SCD-driven MUFA formation facilitates metabolic reprogramming through Akt, AMPK, and NF-κB regulation." (PMID 40381373, 2025). "The mechanism by which SREBP-1 inhibition prevents cancer cell proliferation is through the reduction of SCD-1 expression and disruption of fatty acid desaturation, leading to lipotoxicity due to the abnormally high levels of saturated FAs." (PMID 40137165, 2025). "While SCD expression is generally higher in almost all human cancers compared to normal tissues, there are exceptions." (PMID 41421797, 2025). "SCD represents a new generation of targeted therapy for cancer treatment, as inhibiting SCD can result in three effects: accumulation of free fatty acids (FFAs), increased FAO, and reduced fat storage." (PMID 41421797, 2025). "SCD is highly expressed in several human cancers, such as lung, breast, colorectal, renal, prostate and hepatocellular carcinomas, and is associated with poor survival." (PMID 41306968, 2025). "Studies have shown that inhibition of canonical SCD-mediated desaturation induces apoptosis and growth inhibition in cancer cells through a variety of mechanisms." (PMID 40814339, 2025). "Lipid metabolism-related proteins are therapeutic targets for cancer treatment, for example, targeting the de novo lipogenesis using SCD-1 inhibitors." (PMID 39920872, 2025). "Stearoyl CoA desaturase-1 (SCD), a key regulator of fatty acid metabolic pathways, plays multiple roles in cancer, metabolism, and iron death." (PMID 40360842, 2025). "This further activates stearoyl-CoA desaturase (SCD) by histone acetylation, thus facilitating cancer progression." (PMID 40849305, 2025). "SCD1 has been recognized as a key factor in cancer studies, and its inhibition has been proposed as a potential cancer treatment, due to the reported link between cell proliferation and SCD activity." (PMID 40933871, 2025). "Inhibitors of SCD are thus considered promising candidates for treating metabolic disorders and cancer." (PMID 39966220, 2025). "When combined withDFG-out Raf inhibitors, which block fatty acid desaturation by inducingproteasomal degradation of stearoyl-CoA desaturase (SCD1), LXRαactivation can trigger lipotoxicity-induced cancer cell death." (PMID 40127224, 2025). "Numerous enzymes associated with de novo FA synthesis, such as FASN, ACC, and SCD, are frequently overexpressed in various cancers, thereby boosting FA production and contributing to the malignancy of these tumors." (PMID 39425259, 2025).
cancer (continued). "Here, we conducted an analysis of diverse cancer datasets revealing elevated SCD expression in the PRAD cohort at both mRNA and protein levels." (PMID 39351232, 2024). "Emerging evidence has established a positive association between elevated levels of stearoyl-CoA desaturase 1 (SCD1) and its product oleate (OA) with cancer development and metastasis." (PMID 38612766, 2024). "One proposed mechanism is that SCD promotes the synthesis of monounsaturated fatty acids (MUFAs), such as oleic acid, from saturated fatty acids (SFAs) in cancer cells." (PMID 38610991, 2024). "First, the GEPIA online database was used to analyze the expression level of SCD in different types of human cancer and normal tissues." (PMID 38625951, 2024). "This enrichment implies that SCD upregulation goes beyond a simple correlation, indicating an active role in tumourigenesis by influencing lipid metabolism in a manner conducive to cancer proliferation." (PMID 39107713, 2024). "Using the CancerSEA, we investigated the potential functions of SCD at single cell levels in various cancers." (PMID 39351232, 2024). "Conversely, acyl-CoA synthetase long-chain family member 3 or stearoyl-CoA desaturase (SCD/SCD1) inhibits ferroptosis in cancer cells." (PMID 38594265, 2024). "Lipid metabolic pathways, including fatty acid synthase (FASN) and stearoyl-COA desaturase (SCD) signaling, also sustain cancer stem cells in HCC, contributing to metastasis and drug resistance." (PMID 38297372, 2024). "This is also reflected by the correlation (ELOVL5, FADS2 and ACSL4) and anti-correlation (FASN and SCD) of these enzymes with Zeb1 expression in cancer cell lines." (PMID 39009641, 2024). "Our data are of potential translational relevance and suggest a combination of SCD inhibitors and ferroptosis activators for the treatment of aggressive cancers expressing high Zeb1." (PMID 39009641, 2024). "This emphasizes the potential of SCD upregulation to not only alter cellular metabolic processes but also engage in signaling cascades that are quintessential for cancer progression." (PMID 39107713, 2024). "Compared to FADS2, SCD is more targeted for Asian patients, aged 81–100 years, and with cancer stage 4." (PMID 38905386, 2024). "Key regulators of adipogenesis, including sterol regulatory element binding protein (SREBP), acetyl coenzyme A carboxylase (ACC), FASN and stearoyl coenzyme A desaturase 1 (SCD-1), are detected to be significantly up-regulated in various human cancers." (PMID 38434684, 2024). "Quantification of the online data revealed that over 50% of cancer cases exhibited medium to high expression levels of SCD." (PMID 39351232, 2024). "Our data are of potential translational relevance and suggest a combination of ferroptosis activators and SCD inhibitors for the treatment of aggressive cancers expressing high Zeb1." (PMID 39009641, 2024). "Pan-cancer analysis of SCD transcriptional expression was conducted using the UALCAN platform based on TCGA data." (PMID 39351232, 2024). "Although Stearoyl-coenzyme A desaturase (SCD) is documented to regulate lipid metabolism in multiple cancers, landscape analysis of its implications in PRAD are still missing at present." (PMID 39351232, 2024). "The results highlighted a noteworthy correlation between SCD expression and inflammation in pan-cancer." (PMID 39351232, 2024). "The enhancement of cancer proliferation, metastasis, and lipid metabolism was achieved through the regulation of stearoyl-CoA desaturase mRNA m6A modifications by the IGF2BP3-METTL14 complex." (PMID 38540406, 2024). "The catabolism of lipid droplets allows hypoxic cancer cells to maintain balanced fatty acid saturation when SCD activity is limited, facilitating cancer cell growth in the TME." (PMID 39284708, 2024). "Our previous study revealed that lipid metabolic interaction of CAF and cancer cells promotes tumor progression by SCD-mediated stemness in cancer cells." (PMID 39543650, 2024).
cancer (continued). "This dual mechanism presents a significant barrier to the development of drug resistance, making SCD a promising target for anti-cancer therapy." (PMID 39107713, 2024). "Malignant tumors overexpress SCD, including lung cancer, breast cancer, colorectal cancer, esophageal cancer, bladder cancer, and liver cancer." (PMID 38355626, 2024). "Stearoyl-CoA desaturase 1 (SCD1), an enzyme that catalyzes the rate-limiting step of monounsaturated fatty acid synthesis in cancer cells, is an important regulator of lipid metabolism." (PMID 37818101, 2023). "Tremendous studies have demonstrated that the lipogenic factor SCD is involved in cancer cell proliferation and metastasis." (PMID 36472914, 2023). "Metabolic plasticity in FA desaturation has been recently acknowledged as a relevant phenomenon that supports lipid biosynthesis and confers a metabolic advantage upon SCD inhibition in cancer cells." (PMID 36857618, 2023). "Based on previous findings, several specific inhibitors targeting SCD activity have been developed and are under preclinical tests to treat and/or deal with the chemoresistance of certain types of cancers." (PMID 36472914, 2023). "Stearoyl-CoA desaturase 1 (SCD1), an enzyme involved in lipid desaturation, is crucial in regulating this ratio and has been identified as an important regulator of cancer cell survival and progression." (PMID 37240297, 2023). "SCD is known to be involved in growth and survival of different cancers including breast, lung, liver, colon and pancreas." (PMID 37978383, 2023). "The limiting step in the synthesis of de novo MUFAs, SCD activity, has also been found to be elevated in cancer cells." (PMID 37373069, 2023). "Specifically, targeting key enzymes involved in fatty acid synthesis (SREBP, ACLY, ACC, FASN, and SCD) has been identified as a potential strategy for cancer therapy." (PMID 38189049, 2023). "Cancer cells are resistant to chemotherapy-induced apoptosis partly because of the expression of SCD, which is mediated by phosphatidylinositol three kinase/c-Jun N-terminal kinases activation." (PMID 36950134, 2023). "Evidence indicated that SCD inhibited ferroptosis in cancer cells, and combination therapies of SCD1 inhibitors and ferroptosis inducers had a synergistic effect." (PMID 36815375, 2023). "Stearoyl-CoA desaturase-1 (SCD1), the limiting enzyme for monounsaturated fatty acid synthesis, also shows a robust correlation with cancer development across various cancer types." (PMID 38132455, 2023). "It has been shown that higher SCD levels in cancer cells lead to resistance to ROS induced apoptosis and downregulation of SCD rendered cancer cells that are more sensitive to apoptosis." (PMID 36680249, 2023). "Stearoyl-CoA desaturase 1 (SCD1) functions as a lipid-regulating enzyme in the development of human cancer." (PMID 37259301, 2023). "Sapienate supported cancer cell membrane biosynthesis and proliferation in an SCD-independent way, which increased cancer plasticity." (PMID 37373069, 2023). "Inhibiting SCD-induced accumulation of MUFA leads to cancer cell death, and SCD1 has also been identified as a marker of CSCs in CRC." (PMID 38189049, 2023). "Wnt/β-catenin signalling induces SREBP-dependent transcription of SCD, leading to a positive-feedback loop that regulates lipid homeostasis and can promote liver fibrosis and cancer." (PMID 36763105, 2023). "SCD is over-expressed in multiple malignant tumors, which plays a vital role in regulating proliferation, signal transduction, metastasis and modulates lipid metabolism via reducing fatty acid oxidation to foster lipogenesis." (PMID 38003694, 2023). "SCD is upregulated in the majority of cancers, including ccRCC, and participates in cell metabolism, cell cycle progression, and tumor cell migration." (PMID 36980176, 2023).
cancer (continued). "SREBPs regulate fatty acid and cholesterol metabolism, and their targets genes, such as fatty acid synthase (FASN) and stearoyl-CoA desaturase-1 (SCD1), are therapeutic targets in many cancers." (PMID 37885013, 2023). "SCD is a rate-limiting enzyme in lipid biosynthesis that plays a key role in fuel metabolism and is a potential therapeutic target in cancer treatment." (PMID 36733341, 2023). "Recent research has outlined how SCD influences cancer progression through its effects on lipid metabolism and cell proliferation, migration, invasion, and metastasis." (PMID 37928903, 2023). "Previous studies have reported that overexpression of ACLY/ACSS2/ACC/FASN/SCD promotes tumor cell proliferation, invasion and metastasis in various types of cancer 128-131." (PMID 36778122, 2023). "Dysfunction of SCD in cancer yields an altered level of MUFA, which breaks the balance of MUFA/SFA ratio and change the cellular lipid composition, fluidity and signal transduction to promote cell survival and induce cancer chemoresistance." (PMID 35646898, 2022). "We then found that p73α1 inhibits cancer cell viability through direct transcriptional suppression of Stearoyl-CoA Desaturase-1 (SCD1), which converts saturated FAs to MUFAs." (PMID 36010592, 2022). "Recent studies have shown that increased expression of SCD is correlated with cancer malignancy and promotes cancer stemness." (PMID 36514170, 2022). "In cancer cells, as fatty acid synthesis increases, the conversion of saturated fat to unsaturated fatty acids also increases due to the activity of stearoyl-CoA desaturase (SCD1)." (PMID 35634242, 2022). "For example, Lien and colleagues recently showed that the upregulation of stearoyl-CoA desaturase, which synthesizes MUFAs from SFAs, is essential for cancer cells to grow." (PMID 36382086, 2022). "Cancer cell subclones against stearoyl-CoA desaturase (SCD) were produced by lentiviral vector and CRISPR/cas9 systems." (PMID 36514170, 2022). "The SCD protein is highly expressed in many human cancers, including human colon, esophageal and liver cancers." (PMID 34983949, 2022). "SCD inhibition suppressed cell proliferation and resensitized cancer cells to chemotherapy-induced apoptosis." (PMID 35646898, 2022). "Genetic or pharmacological manipulation of SCD have been shown to impair de novo lipid synthesis, decrease cell proliferation, and increase apoptosis in cancer cells." (PMID 36575190, 2022). "And CAF-derived OA was transferred to cancer cells where they increased SCD expression and promoted stemness via nuclear translocation of yes-associated protein." (PMID 36514170, 2022). "In this study, we investigated the immunological roles of stearoyl-CoA desaturase 1 (SCD1), which is essential for fatty acid metabolism, in the cancer immune response." (PMID 35793868, 2022). "Several studies have demonstrated the involvement of SCD in the promotion of cancer cell proliferation, migration, metastasis, and tumor growth, suggesting this enzyme as a therapeutic target for the treatment of cancer." (PMID 35053112, 2022). "Stearoyl-CoA desaturase (SCD) is essential for the earliest step of autophagosome formation that supports the undisturbed growth of cancer cells." (PMID 36514170, 2022). "For example, stearoyl-CoA desaturase (SCD), an enzyme responsible for the synthesis of monounsaturated FAs, has been found elevated in cancer cells." (PMID 35008394, 2022). "The essential role of SCD-1 in cancer cell mitogenesis was unambiguously demonstrated by several works in which the suppression of SCD-1 by genetic and pharmacological means led to a slower rate of cell proliferation and decreased survival." (PMID 34199164, 2021). "Several SCD inhibitors have been patented for preclinical use against metabolic disorders and cancer." (PMID 33568479, 2021). "In hypoxia, cancer cells deprived of oxygen are unable to maintain proper lipid unsaturation via endogenous SCD activity." (PMID 33466824, 2021).
cancer (continued). "Combined, this suggests that SCD-1 overexpression is only partly responsible for the changes observed in cancer." (PMID 34421820, 2021). "A number of studies have demonstrated that de novo lipogenesis is enhanced in cancer, and SCD-dependent desaturation of the fatty acids is a critical event in this process." (PMID 34564414, 2021). "This is an important issue since increasing attention is being paid to the possibility of using stearoyl-CoA desaturase in the treatment of circulatory diseases and cancers." (PMID 34681339, 2021). "It is also worth mentioning that MUFAs, which can be synthesized by stearoyl-CoA desaturase-1 (SCD1) in human cells, are the main component of TG and that SCD1 is overexpressed in many types of cancer, including CRC." (PMID 34348720, 2021). "SCD plays a major role in control of cancer cell metabolism and its inhibition has been shown to block cancer cell proliferation, reduce their survival, and limit cancer stem cells capacity to initiate tumors." (PMID 34206240, 2021). "For instance, human SCD is critical for growth in many different cancers, particularly in lung cancer, where its expression is inversely correlated with patient survival outcome." (PMID 33466824, 2021). "Among them, SCD-1 was demonstrated to be a key regulator of the MUFA/SFA balance in several cancer cells, and its blockade triggers apoptosis." (PMID 34199164, 2021). "This review describes the regulation of autophagy by lipid metabolism in cancer cells, focusing on the role of stearoyl-CoA desaturase 1 (SCD1), the key enzyme involved in the synthesis of monounsaturated fatty acids." (PMID 34429143, 2021). "This partially can explain why some cancers are insensitive to SCD inhibitors and raises a promising approach of targeting both desaturation pathways for cancer therapy." (PMID 35006438, 2021). "The importance of SCD in membrane function and consequent up-regulation in cancer has been reported in several studies." (PMID 33568479, 2021). "Our findings support the application of cancer therapy that targets the enzymes expressed in the endoplasmic reticulum, such as SCD-1, to CRLM." (PMID 33691644, 2021). "SCD is essential for cancer cell survival, and its anticancer potential has been reported in multiple cancers." (PMID 37849907, 2021). "These specific cancer types are insensitive to pharmacological inhibition of SCD as they upregulate delta-6 desaturase (FADS2) to produce the monounsaturated fatty acyl-CoA sapienyl-CoA (C16:1, n-10) instead of palmitoleoyl-CoA (C16:1, n-9) from palmitoyl-CoA." (PMID 33413672, 2021). "Our finding that a single TF FOSB controls the transcriptional overdrive of SCD in AqR cells in two unrelated cancers is notable." (PMID 33568479, 2021). "Given the importance of SCD in cancer pathology, several SCD inhibitors are being developed for preclinical testing." (PMID 33568479, 2021). "Recently, sapienate (cis-6-C16:1) biosynthesis catalyzed by FADS2 has been identified as another tumor-promoting FA desaturation pathway, which enables cancer cells to by-pass the desaturation pathway dependent on SCD." (PMID 35006438, 2021). "Collectively, these results indicate that global changes in chromatin landscape, gene expression, and signaling occur during the evolution of SCD inhibitor resistance in cancer cells." (PMID 33568479, 2021). "Other studies have also shown that SCD can promote cancer cell proliferation, migration, and metastasis." (PMID 35087751, 2021). "Alongside these recent advances in the understanding of SCD biology and monounsaturated fatty acid production in cancer, an alternative desaturation pathway was recently identified in hepatocellular carcinoma and non-small cell lung cancer." (PMID 33413672, 2021). "Stearoyl-CoA desaturase (SCD) generates monounsaturated fatty acids in cancer cells by catalyzing the formation of double bonds at Δ9 position of palmitoyl-CoA and stearoyl-CoA32,33." (PMID 33446752, 2021).